STAT5B (signal transducer and activator of transcription 5B)
Diseases named in the same sentence as STAT5B in open-access papers (continued):
Sharing a sentence is not in itself a finding about the gene and the disease.
breast cancer (continued). "It seems, however, that the role of STAT5B in the development of lung cancer is more similar to that in prostate cancer than in breast cancer." (PMID 25137041, 2014). "In the present study, which focused on PRL-modulated transcripts in the T47D breast cancer model, experimental overexpression of Stat5a or Stat5b enhanced to a comparable extent PRL-modulation of most transcripts tested." (PMID 23758962, 2013). "Future transcript analyses will focus on further characterizing the differences in gene regulation between Stat5a and Stat5b in human breast cancer." (PMID 23758962, 2013). "In contrast, Stat5b protein levels remained unchanged, suggesting divergent expression and involvement of Stat5a and Stat5b during breast cancer progression." (PMID 23036105, 2012). "Stat5a and Stat5b transcript levels in breast cancer were correlated with clinical outcome in 936 patients." (PMID 23036105, 2012). "In MCF-7 human breast cancer cells, expression of selected genes also differed after stable introduction of constitutively active Stat5a or Stat5b." (PMID 23036105, 2012). "Novel functions of STAT5b, a new target for breast tumor kinase/protein tyrosine kinase 6 (Brk/PTK6), have been reported and the involvement of STAT5b in breast cancer cell migration has been demonstrated." (PMID 22485142, 2012). "STAT5b is a transcription factor involved in the proliferation and survival of many solid tumors, including breast cancer." (PMID 22792362, 2012). "Furthermore, the mechanisms underpinning loss of Nuc-pYStat5a/b in breast cancer remain to be identified, and it is unknown whether reduced Nuc-pYStat5a/b levels in breast cancer may in part reflect reduced levels of Stat5a and/or Stat5b protein expression." (PMID 23036105, 2012). "Although the new data provide clarity about Stat5a and Stat5b in breast cancer, several limitations of this study exist." (PMID 23036105, 2012). "In contrast, Stat5b has been reported to contribute to the progression of established breast cancer." (PMID 23036105, 2012). "With selective Stat5a and Stat5b antibodies and immunofluorescence detection on the Automated Quantitative Analysis (AQUA) platform, Stat5a and Stat5b protein levels were quantified in breast cancer progression material." (PMID 23036105, 2012). "Collectively, these discrepant and incomplete data warrant a more systematic effort to quantify Stat5a or Stat5b protein expression during human breast cancer progression relative to normal breast tissue." (PMID 23036105, 2012). "The activation of STAT5b and phosphorylation is mediated by several kinases overexpressed in breast cancer." (PMID 22792362, 2012). "Based on the data presented here, we postulate that unphosphorylated STAT5b mediates migration of breast cancer cells through regulation of cytoplasmic Rho GTPase family signaling." (PMID 19630967, 2009). "The work presented here establishes an important, previously undiscovered role for STAT5b in the migration of highly aggressive breast cancer cells." (PMID 19630967, 2009). "We sought to determine the serum component responsible for migration of breast cancer cells as a means of gaining insight into those migratory signaling pathways to which STAT5b contributes." (PMID 19630967, 2009). "The importance of STAT5b in mediating breast cancer cell proliferation and survival has already been established." (PMID 19630967, 2009). "This will facilitate the long-term goal of defining conditions whereby STAT5b would be an effective therapeutic target for the treatment of breast cancer." (PMID 19630967, 2009). "The data presented here demonstrate that STAT5b is integral to breast cancer cell migration and identify a novel, SH2-dependent function of STAT5b in regulating β1-integrin-mediated migration of highly aggressive breast cancer cells." (PMID 19630967, 2009). "In summary, these studies are the first to report a role for STAT5b in the migration of breast cancer cells." (PMID 19630967, 2009).
breast cancer (continued). "It is well established that STAT5b promotes cell-cycle progression and survival of breast cancer cells." (PMID 19630967, 2009). "This work is the first to show a positive regulatory role for STAT5b in breast cancer cell migration." (PMID 19630967, 2009). "Given this background, we sought to investigate the potential role of STAT5b, specifically, in the migration of two highly aggressive, highly migratory breast cancer cell lines." (PMID 19630967, 2009). "After establishing the necessity of STAT5b for maximal migration of breast cancer cells to serum, we investigated the mechanism by which this occurs." (PMID 19630967, 2009). "Taken together, these results demonstrate that STAT5b is integral for β1-integrin-mediated migration of breast cancer cells to FN." (PMID 19630967, 2009). "To determine the importance of STAT5b for breast cancer cell migration, we used siRNA transfection to knock down STAT5b in the highly migratory BT-549 breast cancer cell line." (PMID 19630967, 2009). "It is well established that STAT5b positively regulates breast cancer cell proliferation and survival, two processes important for initial tumor formation and growth." (PMID 19630967, 2009). "We showed previously that EGF stimulation of breast cancer cells leads to phosphorylation of STAT5b on Y699 and subsequent transcriptional activity." (PMID 19630967, 2009). "Since activating mutations in STAT5b have not been found in breast cancer, it is important to look upstream to identify the kinases that regulate STAT5b, thus potentially leading to its increased activity in breast cancer cells." (PMID 17997837, 2007). "The results of siRNA experiments suggest that Brk and STAT5b are in the same signaling pathway, which ultimately leads to the proliferation of breast cancer cells." (PMID 17997837, 2007). "Using our previously characterized STAT5b-specific antibodies, we demonstrated here that Brk can also directly phosphorylate Y699 on STAT5b in breast cancer cell lines and in an in vitro kinase assay." (PMID 17997837, 2007). "While studies in the MEF5-/- cells allowed us to characterize the role of Brk in STAT5b activation, we continued our studies in breast cancer cell lines as a means to investigate the biological relevance of Brk-mediated STAT5b activation." (PMID 17997837, 2007). "Together, these data establish a fundamental role for STAT5b in the process of breast cancer tumorigenesis." (PMID 17997837, 2007). "We propose that Brk, like other tyrosine kinases, signals downstream to STAT5b to mediate proliferation of breast cancer cells." (PMID 17997837, 2007). "Based on our studies, we propose that HER2, EGFR, c-Src, and Brk all signal downstream to STAT5b to increase proliferation of breast cancer cells." (PMID 17997837, 2007). "Since STAT5b mediates breast cancer proliferation, identification of kinases that increase STAT5b activity is critical to identifying potential therapeutic targets." (PMID 17997837, 2007). "Since evidence supports the involvement of both Brk and STAT5b in breast cancer proliferation, we investigated the ability of Brk to phosphorylate STAT5b and the biological significance of this activation." (PMID 17997837, 2007). "STAT5b phosphorylation and activation is mediated by several kinases known to be overexpressed in breast cancer, such as epidermal growth factor receptor, HER2, and c-Src." (PMID 17997837, 2007). "siRNA technology was utilized to investigate the biological significance of Brk-induced activation of STAT5b in breast cancer cell models." (PMID 17997837, 2007). "Inhibition of STAT5b via dominant-negative constructs and siRNA technology decreases DNA synthesis, while exogenous expression of a basally active STAT5b mutant (Y740/743F) increases DNA synthesis of breast cancer cells." (PMID 17997837, 2007). "In Brk-positive breast cancer cell lines BT-20 and SKBr3, knockdown of Brk protein or of STAT5b protein using siRNA methodology resulted in a decrease in DNA synthesis." (PMID 17997837, 2007).
breast cancer (continued). "Furthermore, METTL3 has been found to interact with the transactivation domain of EGF-induced STAT5B in the nucleus of breast cancer cells." (PMID 40507264, 2025). "Enrichment analysis of STAT5B in breast cancer were also conducted." (PMID 36862902, 2023). "Moreover, STAT5B expression in invasive ductal breast carcinoma was significantly lower than normal breast cancer (FC = −2.087, P = 4.17E–79)." (PMID 36862902, 2023). "In this study, bioinformatics analysis showed that low STAT5B expression was significantly present in patients with breast cancer and could be involved as a key regulatory element in facilitating cancer cells' progression." (PMID 35928368, 2022). "Taken together, our studies have demonstrated essential role of ERα and STAT5b in EGF/EGFR induced activation of PRLR gene transcription/expression in breast cancer cells via STAT5b interaction with ERα and complex formation with Sp1/C/EBPβ at the PRLR promoter in the absence of estrogen." (PMID 27564112, 2016). "We predicted that specific blocking of STAT5b in human breast cancer cells by HS may enhance solid cancer cell apoptosis." (PMID 22792362, 2012). "STAT5b is identified as an integral factor for breast cancer cell migration." (PMID 22792362, 2012). "Stat5a and Stat5b protein levels were quantified in situ in breast-cancer progression material." (PMID 23036105, 2012). "Furthermore, prolactin-suppression of the Bcl6 oncogene in human breast cancer cell lines was preferentially mediated by Stat5a over Stat5b." (PMID 23036105, 2012). "Low transcript levels for Stat5a but not Stat5b in breast cancer specimens were associated with poor clinical outcome." (PMID 23036105, 2012). "STAT5b is involved in the β1-integrin mediated migration of breast cancer cells." (PMID 22792362, 2012). "Current data support the concept of dual roles of Stat5a/b proteins as promoters of mammary tumorigenesis, and as suppressors of the progression of established breast cancer, although our knowledge of individual roles of Stat5a and Stat5b in breast cancer remains rudimentary." (PMID 23036105, 2012). "Our studies demonstrate a novel function of STAT5b in breast cancer cell migration." (PMID 19630967, 2009). "This work aims to elucidate the role of STAT5b in breast cancer cell migration." (PMID 19630967, 2009). "Furthermore, analysis of DNA synthesis suggests that STAT5b and Brk are converging upon the same proproliferative signaling pathway in breast cancer cells." (PMID 17997837, 2007). "Given the evidence that we have provided for the functionally relevant regulation of STAT5b by Brk, further pursuing the role of this Brk–STAT5b pathway in breast cancer may provide important novel therapeutic targets." (PMID 17997837, 2007). "STAT5b is more abundantly expressed than STAT5a in prostate cancer and breast cancer cell lines." (PMID 17997837, 2007). "Since both c-Src and Brk tyrosine kinases are frequently overexpressed in breast cancer and since they both mediate Y699 phosphorylation of STAT5b, there is potential for these kinases to either substitute for one another or work together to activate STAT5b." (PMID 17997837, 2007). "STAT5B has been implicated in migration, whereas loss of STAT5A was associated with disease progression, highlighting the importance in future studies to distinguish between the two STAT5 proteins to enrich clinical efficacy of STAT5 as a biomarker for breast cancer." (PMID 40507264, 2025). "We identified 7 genes (ITGB1, SNAI1, NOTCH4, STAT5B, RAPGEF3, LAMA2, and GNAI1) that have been implicated in both stemness and the drug response and validated their relevance through an analysis of data from breast cancer patients in the TCGA database using UCSC Xena." (PMID 39180549, 2024). "In addition, we found that high mRNA expression STAT5a and STAT5b is significantly associated with RFS in breast cancer patients, implying that STAT5 may be an important promising biomarker for breast cancer." (PMID 29326301, 2018).
breast cancer (continued). "However, decreased STAT5B expression was not directly associated with breast cancer invasion." (PMID 35928368, 2022). "The large majority (10/13) of these genes were reported to play a role in the regulation of estrogen and/or progesterone response in human breast cancer (NCOA7:; NCOA3:; USP22:; MED24:; CCAR1:; CRY2:; STAT5B:; PAGR1:; TAF1:; PHB2:)." (PMID 35996163, 2022). "BRK was shown to phosphorylate STAT5b on Y699, which enhanced STAT5b transcriptional activity and suggests that BRK signals downstream to STAT5b to mediate the proliferation of breast cancer cells." (PMID 24523872, 2014). "Both STAT5A and STAT5B are key tumor growth stimulators, but STAT5B overexpression seems to be more significant in head and neck and prostate cancers, while STAT5A – in breast cancer." (PMID 25137041, 2014). "HSE effectively down-regulated the expression of Brk in breast cancer cell lines by the activation of STAT3 and STAT5b." (PMID 22792362, 2012). "Recently, we reported that STAT5b regulates the transactivation of cyclin D1 and IGF-1 upon hypoxia stimulation in breast cancer cells." (PMID 22485142, 2012). "However, Stat5b mRNA levels were not informative about the risk of breast cancer relapse." (PMID 23036105, 2012). "Knockdown of STAT5b inhibits migration of BT-549 and MDA-MB-231 human breast cancer cells to serum and fibronectin." (PMID 19630967, 2009). "We found that STAT5b knockdown inhibited serum- and fibronectin-stimulated migration of both BT-549 and MDA-MB-231 human breast cancer cell lines in a transwell assay." (PMID 19630967, 2009). "STAT5b was knocked down by using siRNA in two aggressive, highly migratory breast cancer cell lines (BT-549 and MDA-MB-231), and transwell migration assays were performed to determine the importance of STAT5b for their migration." (PMID 19630967, 2009). "Previous studies have demonstrated that STAT5a and STAT5b are tyrosine phosphorylated by the EGFR and c-Src kinases, two kinases that are involved in breast cancer." (PMID 17997837, 2007). "Both STAT5b and STAT3 are activated by several kinases overexpressed in breast cancer, including the EGFR, HER2, and c-Src." (PMID 17997837, 2007). "Interestingly, expression of some immune cell genes and DVL-1 uniquely correlated with luminal breast cancer, such as CD19, CD79A, CD8B, CCR7, CD1C, and STAT5B." (PMID 34659647, 2021). "In breast cancer, HOXA1 transforms immortalized human breast epithelial cells stimulated by p44/42 MAPK pathway, signal transducer and activator of transcription 3 (STAT3) and STAT5B into an invasive malignant phenotype." (PMID 33763449, 2020). "STAT2, STAT4, STAT5a, STAT5b, and STAT6 had significantly favorable effect on RFS of breast cancer patients, but STAT1 had significant worse effect on RFS; STAT5b had significant favorable effect on PPS, while, STAT2 had significant worse effect on PPS for breast cancer patients." (PMID 29326301, 2018). "Moreover the participation of a Cas/cSarc/pEGFR/pSTAT5b pathway in tamoxifen resistance ERα+ T47D breast cancer cells is reversed by dominant negative Y845F EGFR and C-terminal truncated STAT5b." (PMID 25193864, 2014). "We have recently reported that Stat5a but not Stat5b expression was lost during progression of human breast cancer, and in cultured MCF-7 cells there was only a limited overlap in transcripts modulated by the two PRL-activated transcription factors." (PMID 23758962, 2013). "These quantitative in situ data provided novel information indicating that levels of Nuc-Stat5a, but not Nuc-Stat5b, are reduced over breast cancer progression." (PMID 23036105, 2012). "We previously reported that STAT5b may mediate the transcriptional activation of IGF-1 and cyclin D1 after hypoxic stimulation in human breast cancer cells." (PMID 22485142, 2012). "Protein levels of Stat5a but not Stat5b were reduced in primary breast cancer and lymph node metastases compared with normal epithelia." (PMID 23036105, 2012).
breast cancer (continued). "In addition, HSE treatment inhibited STAT5b/IGF-1R and STAT3/VEGF-dependent luciferase activities in breast cancer cells." (PMID 22792362, 2012). "We and others found that STAT5b is the predominant STAT5a/b protein expressed in breast cancer cell lines and tissues, and that STAT5b, not STAT5a, mediates proliferation of breast cancer cells." (PMID 19630967, 2009). "To date, most of the work examining STAT5b in breast cancer has focused on its pro-proliferative function, and its role in breast cancer cell migration has not been examined." (PMID 19630967, 2009). "We chose to use the MDA-MB-231 breast cancer cell line because they are highly migratory and express both STAT5a and STAT5b proteins, whereas BT-549 breast cancer cells express only STAT5b (data not shown)." (PMID 19630967, 2009). "STAT5B is the predominant form of STAT5 in breast tumour cell lines including SKBR3 and most likely contributes to the elevated expression of HSP90α in breast cancer cells." (PMID 19014541, 2008). "Exogenous expression of Brk in the Brk-negative breast cancer cell line BT-549 increased endogenous STAT5b transcriptional activity." (PMID 17997837, 2007). "Recent evidence indicates that STAT5b, but not STAT5a, has a proproliferative role in breast cancer, head and neck cancer, and prostate cancer." (PMID 17997837, 2007). "We have demonstrated that the nonreceptor tyrosine kinase Brk positively regulates STAT5b activity leading to proliferation of breast cancer cells." (PMID 17997837, 2007). "Therefore, STAT5b is necessary for optimal migration of highly aggressive breast cancer cells, whereas expression of STAT5a is not required and cannot compensate for loss of STAT5b." (PMID 19630967, 2009). "The contribution of STAT5b to breast cancer cell motility has not been explored." (PMID 19630967, 2009). "Since our previous studies demonstrated that STAT5b, but not STAT5a, elicits a proproliferative effect in breast cancer cells, and other studies have shown that Brk also increases proliferation of breast cancer cells, we focused our efforts on Brk-mediated activation of STAT5b." (PMID 17997837, 2007). "Although STAT5A and STAT5B are often grouped together as STAT5, it is important to note that some differences between the two have been shown in normal mammary gland and breast cancer." (PMID 40507264, 2025). "Specifically, METTL3 association with the CCND1 (cyclin D1) promoter region was reduced with STAT5B knockdown, but not STAT5A, which impaired cell cycle progression in hormone receptor-positive MCF7 breast cancer cells." (PMID 40507264, 2025). "Stat5b but not Stat5a promoted in vitro migration of ER-negative BT549 and MDA-MB-231 breast cancer cells." (PMID 23036105, 2012). "Western blotting studies showed that MSM can effectively down-regulate the expression of STAT5b as well as IGF-1R in both aggressive and non-aggressive human breast cancer cell lines." (PMID 22485142, 2012). "To ensure that this effect was not unique to one cell line, we tested the effect of STAT5b siRNA knockdown on migration of MDA-MB-231 cells, another highly aggressive, migratory breast cancer cell line." (PMID 19630967, 2009). "Knockdown of STAT5b, but not STAT5a, inhibited migration of BT-549 and MDA-MB-231 breast cancer cells to serum by 60% to 80%, and inhibited migration equally over a range of serum concentrations (0.1% to 10% serum)." (PMID 19630967, 2009). "We have not examined the contribution of STAT5B in our study, although it has been suggested that the balance between STAT5A and B expression may be important in breast cancer progression." (PMID 24913037, 2014).